GHSR (growth hormone secretagogue receptor)
Diseases named in the same sentence as GHSR in open-access papers (continued):
Sharing a sentence is not in itself a finding about the gene and the disease.
Obesity (continued). "To further study GHSR in a condition that better resembles what is observed in humans who have prolonged exposure to high-calorie food and develop obesity, we investigated the role of GHSR, in GHSR-KO and WT rats of both sexes, that were exposed to an HFD for 12 months." (PMID 38796563, 2024). "Our previous study showed that neuronal GHSR deletion prevents high-fat diet-induced obesity (DIO)." (PMID 38464534, 2024). "The ghrelin receptor (GHSR) has ligand-independent actions, therefore, GHSR gene deletion may be a reasonable approach to investigate the role of this system in feeding behaviors and diet-induced obesity (DIO)." (PMID 37886546, 2023). "Our results support GHSR as a promising target for new pharmacotherapies for obesity." (PMID 37886546, 2023). "These factors might involve changes to GHSR signaling present in the setting of diet-induced obesity besides reductions in circulating ghrelin." (PMID 38099492, 2023). "Functionally, the decrease in ghrelin/LEAP2 ratio in T2D patients may reduce the over-activation of GHSR in obesity to return to normal energy homeostasis." (PMID 35521798, 2022). "However, it is still necessary to establish the relationship between the 5HT2c receptor and GHSR, as well as and other receptor subtypes on appetite and obesity." (PMID 35047549, 2021). "Besides the direct effect of ghrelin elimination on macrophages polarization, the decrease of food intake in GHSR knockout mice should also be considered, which will in turn promote the resistance to high fat diet-induced obesity and adipose inflammation." (PMID 30112394, 2018). "It was later reported that GHSR antagonism may also retard the development of ovariectomy-induced obesity in female mice." (PMID 28398233, 2017). "As in mice lacking ghrelin, mice deficient for GHSR are protected from diet-induced obesity (DIO) when fed a HFD." (PMID 26042199, 2015). "A rare functional GHSR promoter mutation variant was identified, yet there was no consistent relationship with obesity in neither family- nor population-based studies." (PMID 20404923, 2010). "In summary, common variants in GHSR did not associate with measures of obesity or overweight in the general population of Danes." (PMID 20404923, 2010). "In the present study, we tested the hypothesis that common and rare variation in the GHSR locus are related to increased prevalence of obesity and overweight among Whites." (PMID 20404923, 2010). "In recently conducted genome-wide association (GWA) studies, GHSR was not among the few genes associated with obesity or type 2 diabetes." (PMID 18698404, 2008). "The present study aims to investigate the association of GHSR-1a immunopositive (+) cells from atherosclerotic plaque and PVAT with inflammatory markers (tissue concentrations of CRP, Il-6, leptin, and adiponectin) by studying the arteries harvested from patients with obesity and PAD." (PMID 40137085, 2025). "First, we investigated whether β-cell GHSR regulated insulin secretion under HFD-induced obesity." (PMID 38794702, 2024). "Data obtained by us and others on the ablation of all three components of the GOAT-ghrelin-GHSR axis in mice on an ob/ob background further demonstrate that neither desacyl nor acyl ghrelin (signaling) can reverse the massive obesity induced by leptin deficiency." (PMID 23630616, 2013). "Thus, common GHSR variants are most likely not major contributors to obesity among Caucasian individuals." (PMID 20404923, 2010). "Whilst, it can not be ruled out that this rare GHSR promoter variant may contribute modestly to the pathogenesis of obesity it would require a much larger study sample to investigate this." (PMID 20404923, 2010). "However, our study may help to understand whether the anti-inflammatory action of ghrelin in PAD mediated by GHSR-1a can be considered a compensatory immune response and how the obesity-related PVAT dysfunction and old age can reverse this anti-inflammatory effect." (PMID 40137085, 2025).
Obesity (continued). "This study suggests that ghrelin/GHSR signaling promotes lipid uptake and WAT accumulation via endothelial cells, making this pathway a promising therapeutic target for obesity and dyslipidemia." (PMID 39796581, 2024). "Neuronal deletion of the growth hormone secretagogue receptor (GHS-R), a receptor responsible for mediating ghrelin’s effects on appetite pathways, has resulted in reductions in diet-induced obesity and insulin resistance." (PMID 35328862, 2022). "This view is supported by a report that obesity and diabetes were improved by reducing acyl ghrelin levels, increasing LEAP2 levels, or blocking GHSR activity." (PMID 35521798, 2022). "This pattern suggests that under standard diet conditions (with or without BCP supplementation) GHSR expression remains at lower levels than those observed in obesity conditions." (PMID 41149616, 2025). "Of particular interest, in the stress-induced obesity, HTR2A interacts with CCK and GHSR." (PMID 39062927, 2024). "In conclusion, we demonstrated a protective effect of GHSR deletion in diet-induced obesity in male, but not female, rats, which shows a dramatic sexual dimorphism." (PMID 38796563, 2024). "Of note, the studies summarized above looked at GHSR-KO, PF-5190457, or both in the context of food seeking and diet-induced obesity without any alcohol-related experiments." (PMID 39704175, 2024). "GHSR deletion throughout the body prevents HFD-induced adiposity and body weight gain, and therefore, we investigated the role of endothelial GHSR in the development of obesity after an HFD." (PMID 39796581, 2024). "In ghrelin or GHSR null mice, studies reveal they have similar body weight compared to littermates and are not resistant to diet-induced obesity but have been shown that under caloric-restriction there is impaired maintenance of glucose homeostasis." (PMID 36291579, 2022). "Orexigenic and pro-obesity effects of intra-lPBN delivery of ghrelin have since been reported in mice and shown to require endogenous GHSR signaling, since they were absent in GHSR knockout mice." (PMID 33658910, 2021). "Notably, the studies reported here unmasked a dramatic sexually dimorphic phenotype as the deletion of GHSR protected against obesity in male, but not female, HFD-fed rats." (PMID 38796563, 2024). "However, in our study, β-cell-specific GHSR deficiency did not alter HFD-induced glucose intolerance or insulin secretion, suggesting differential effects between ghrelin and GHSR under obesity." (PMID 38794702, 2024). "However, the role of β-cell GHSR under HFD-induced obesity and normal aging processes have not been thoroughly examined." (PMID 38794702, 2024). "Collectively, although the impact of GHSR deficiency was observed during the early stages of HFD administration, it did not significantly alter insulin secretion, glucose intolerance, nor insulin sensitivity in HFD-induced obesity." (PMID 38794702, 2024). "A more recent study, however, could not point out a clear relationship between GHSR SNPs and obesity." (PMID 18698404, 2008). "While we and others could not detect any GHSR localization in the collecting duct there still seems to be a role for GHSR regarding ENaC stimulation in the collecting duct resulting in obesity- and angiotensin-II-mediated hypertension." (PMID 38638279, 2024). "Specifically, B. longum may decrease the GHSR-1a internalization and has been correlated with its higher acetate content, but also with decrease body weight gain, fat depot size, glucose tolerance, and leptin levels in a preclinical mouse model of HFD-induced obesity." (PMID 34458288, 2021).
Cachexia (27 papers, 2015 to 2026). Severe weight loss, wasting of muscle, loss of appetite, and general debility related to a chronic disease. "Experimental strategies to preserve skeletal muscle mass include blocking myostatin signaling, and antagonizing the growth hormone secretagogue receptor (GHSR)-1a, and have been shown to improve survival in mice with cancer cachexia." (PMID 31032492, 2019). "Analogously, administration of ghrelin, an endogenous ligand for the growth hormone secretagogue receptor (GHSR)-1a, was shown to protect against cisplatin-induced cachexia by promoting muscle anabolism in experimental animals." (PMID 27259276, 2016). "The objectives of the current study were: 1) to characterize the pathways involved in adipose tissue atrophy in the LLC-induced cachexia model; and 2) to determine the pathways mediating the effects of ghrelin on adipose tissue and the relative contribution of GHSR-1a." (PMID 32934774, 2020). "Recent clinical trials demonstrated that the ghrelin/growth hormone secretagogue receptor agonist anamorelin increases lean body mass and improves the performance status in NSCLC patients with cachexia." (PMID 31906082, 2019).
Insulin resistance (25 papers, 2010 to 2025). Increased resistance towards insulin, that is, diminished effectiveness of insulin in reducing blood glucose levels. "In addition, we found that global GHSR ablation alleviates age-related obesity and insulin resistance by promoting thermogenesis, and our collective work showed that the deletion of GHSR in Kiss1 neurons reduces DIO-associated anxiety-like behavior." (PMID 38464534, 2024). "AG induces growth hormone (GH) secretion, increases food intake, and promotes adiposity and insulin resistance via its receptor, Growth Hormone Secretagogue Receptor (GHS-R)." (PMID 34368393, 2020). "This reduction in glucose levels was accompanied by a moderate decrease in serum insulin levels, suggesting that GHSR antagonists ameliorated insulin resistance in the long term." (PMID 20700401, 2010). "Suggesting ghrelin mimetic-mediate GH-independent insulin resistance, moreover several studies have demonstrated that interference with ghrelin signalling by use of GHSR antagonist decreases blood glucose in wild-type mice as well as GH-deficient lit/lit mice." (PMID 20700401, 2010). "Under DIO, β-cell GHSR deficiency did not exhibit a notable effect on body weight/fat, fed blood glucose, glucose intolerance, nor insulin resistance." (PMID 38794702, 2024). "GHSR is also known for its association with aging, and we previously reported that the ablation of GHSR suppresses age-related changes in adipose/hepatic inflammation and insulin resistance, and we recently reported that macrophage GHSR controls systemic inflammation and insulin resistance in DIO." (PMID 38794702, 2024). "Finally, ghrelin, a ligand for growth hormone secretagogue receptor, is downregulated in aging and morbid obesity, which are insulin resistance states." (PMID 25035815, 2013). "Suppressing GHSR in β-cells may offer a novel therapeutic strategy for preserving β-cell resilience and improving β-cell function, protecting against inflammation and insulin resistance in the aging pancreatic islets." (PMID 38794702, 2024). "Furthermore, up-regulation of hypothalamic AG and GHSR-1a showed positive correlations with homeostatic model assessment insulin resistance (HOMA-IR) and hepatic triglycerides (TGs), respectively, The results suggest a potential benefit of AG blocking to NAFLD." (PMID 36246070, 2022). "This defense mechanism against insulin resistance could be realized through the receptors G-protein-coupled receptor (GPCR), growth hormone secretagogue receptor (GHSR), and growth hormone-releasing hormone receptor (GHRHR)." (PMID 33959145, 2021). "However, in aging mice, knockout of GHSR did not affect the body weight and food intake, although adipose tissue inflammation and insulin resistance were improved." (PMID 30112394, 2018). "Wild type mice fed with high fat diet demonstrated severe hyperglycemia upon administration of glucose and impaired glucose tolerance, with typical glucose disposal curves of insulin resistance, whereas the glucose metabolism was not affected by high fat diet in GHSR-/- mice." (PMID 30112394, 2018).
Anxiety (22 papers, 2010 to 2025). Intense feelings of nervousness, tension, or panic often arise in response to interpersonal stresses. "Furthermore, we utilized an AAV vector to overexpress the GHSR in the NAc core and examined its effect on anxiety-like behaviors caused by acute restraint stress." (PMID 38965529, 2024). "Interestingly, ghrelin and GHSR function are also linked with reduced anxiety-like and depressive-like behavior, including following olfactory bulbectomy in mice, although the main sites of action have not been fully elucidated." (PMID 39236785, 2024). "Thus, it is likely that some of the behavioral outcomes associated with these anxiety and depressive-like behaviors may be related to the protective effects of GHSR signaling in the VTA." (PMID 38937108, 2024). "Overall, our data indicate that ghrelin signaling in the NAc core actively participate in the modulation of anxiety, and ghrelin/GHSR signaling represents a therapeutic target for novel interventions in anxiety disorders." (PMID 38965529, 2024). "This study demonstrates that ghrelin and its receptor GHSR in the NAc core are actively involved in modulating anxiety induced by acute stress, and raises an opportunity to treat anxiety disorders by targeting ghrelin signaling system." (PMID 38965529, 2024). "In the present study, we explored the role of NAc core ghrelin/GHSR signaling system in the acute restraint stress-induced anxiety-like behaviors in rats." (PMID 38965529, 2024). "More importantly, our data further reported that increased GHSR signaling in the NAc core was sufficient to ameliorate anxiety-like behaviors in pathological acute stress conditions." (PMID 38965529, 2024). "In summary, we show that selective GHSR deletion in the OB suppresses normal olfactory function, decreases odor-based food-seeking, and exploratory locomotion and leads to anxiety- and depressive-like behaviors." (PMID 39236785, 2024). "Many studies in rodents suggest that ghrelin and the GHSR play a role in the regulation of fear and anxiety-like behaviors." (PMID 36846243, 2023). "Several rodent studies point to a positive effect of ghrelin receptor (GHSR) agonism on fear- and anxiety-like behaviors." (PMID 36846243, 2023). "Taken together, these findings suggest that ghrelin and GHSR are important for the ability of animals to cope with anxiety-inducing stressors." (PMID 36672651, 2023). "In summary, our findings are in contrast to several studies reporting beneficial effects of GHSR agonism and overnight fasting on fear- and anxiety-related behaviors in rodents." (PMID 36846243, 2023). "Recent studies have shown that ghrelin and its receptor, the growth hormone secretagogue receptor (GHSR), play important roles in mediating stress, as well as anxiety and depression-like behaviors in animal models." (PMID 36672651, 2023). "Here, we investigated the effects of chronic tetrahydrocannabinol (THC) administration during late adolescence (P42–55) in GHSR (GHSR −/−) knockout mice and their wild-type littermates in relation to anxiety-like behaviors." (PMID 36672651, 2023). "This indicates that in chronic caloric restriction, the body resists anxiety and depression in a GHSR-independent manner, which is different from the effect in acute caloric restriction." (PMID 36235843, 2022). "Nevertheless, many studies suggest beneficial effects of GHSR agonism and fasting on fear, anxiety-, and depression-like behaviors." (PMID 33192444, 2020). "In GHSR-KO mice, however, acute food deprivation enhanced, while only chronic caloric restriction reduced anxiety- and depression-like responses." (PMID 33192444, 2020). "Next, we determined whether NAc core ghrelin/GHSR signaling regulated anxiety symptoms in a model of acute restraint stress." (PMID 38965529, 2024). "Knockdown of NAc core GHSR increased anxiety-like behaviors." (PMID 38965529, 2024). "Molecular upregulation of GHSR in the NAc core ameliorated acute restraint stress-induced anxiety." (PMID 38965529, 2024).
Anxiety (continued). "Moreover, we utilized molecular approaches to examine the role of NAc core ghrelin/GHSR signaling in the anxiety-like behaviors." (PMID 38965529, 2024). "GHSR and ghrelin knockout mice showed decreased plasma levels of corticosterone after chronic social defeat stress and acute restraint stress, as well as increased anxiety-like behavior." (PMID 36672651, 2023). "Several studies have demonstrated that caloric restriction or short-term fasting strongly facilitate within-session fear extinction and extinction memory formation in extinction-competent mice or reduce anxiety-like behaviors via different mechanisms, but probably also in a GHSR-dependent manner." (PMID 36846243, 2023). "Furthermore, rescue of the GHSR in tyrosine hydroxylase positive cells restores both food preference and reduces social anxiety in stressed GHSR KO mice." (PMID 33879778, 2021). "Also, caloric restriction may have beneficial effects on fear, anxiety- and depression-like behaviors in unstressed rodents through activation of GHSR." (PMID 33192444, 2020). "Certainly, it is crucial that these differences in the proposed action of ghrelin on anxiety-like behaviors be resolved given the impact that they might have on the side-effect profile of any GHSR antagonist in development as an antiobesity or antidiabetes agent." (PMID 20721341, 2010). "To determine the endogenous ghrelin signaling system in the regulation of anxiety, we generated AAV vectors to knockdown the expression of GHSR in the NAc core." (PMID 38965529, 2024). "Our studies, however, focussed on the GHSR and highlight an important and unappreciated physiological role for OBGHSR signalling to alleviate anxiety-like and depressive-like behaviors, as well as enhance exploratory behavior, particularly in the fasted state." (PMID 39236785, 2024). "In particular, it has become apparent that ghrelin directly affects anxiety, stress, and fear-related behaviors by virtue of its actions on “GHSR,” the growth hormone secretagogue receptor." (PMID 28712092, 2018). "Mice lacking central GHSR expression do not increase food intake in response to chronic social defeat and show more depressive- and anxiety-like behaviors following this social stress paradigm than WT mice do." (PMID 38937108, 2024). "The current study demonstrates that NAc core ghrelin/GHSR signaling holds a critical role in regulation of anxiety-like behaviors under non-stressed and acute stressed conditions, which raises a potential therapeutic target to treat anxiety disorders." (PMID 38965529, 2024). "This led us to conclude that intact GHSR signaling is no pre-requisite to extinguish fear and that GHSR dysfunction per se has no influence on fear and anxiety-related behaviors." (PMID 36846243, 2023). "A local knockdown of the GHSR in the hippocampus also aggravated anxiety- and depression-like behaviors in mice following exposure to a CSDS or CUMS paradigm, pointing to a protective role of the GHSR during chronic stress." (PMID 33192444, 2020). "A similar trend can be observed in pharmacological studies using GSHR ligands, where, without prior stress exposure, GHSR agonists predominantly promote anxiety- and depression-like behaviors, but seem to reduce chronic stress-related phenotypes." (PMID 33192444, 2020). "Under non-stressed conditions, no or only marginal effects on fear, anxiety- and depression like behaviors were observed in GHSR KO mice compared to wild type controls." (PMID 33192444, 2020). "This seems most obvious for GHSR signaling, which does not appear to affect fear, anxiety- and depression-like behaviors under non-stressed conditions but may exert mostly protective effects during chronic stress." (PMID 33192444, 2020).